ALK (ALK receptor tyrosine kinase)
Diseases named in the same sentence as ALK in open-access papers (continued):
Sharing a sentence is not in itself a finding about the gene and the disease.
tumor (continued). "Interestingly, activation of downstream targets of ALK has also been observed in NB tumours without ALK mutation or amplification; it appears that the wild-type receptor requires a critical level of expression to permit constitutive signaling." (PMID 29642598, 2018). "Even the current intensive polychemotherapy may boost the anti-tumor immune response in some patients, as suggested by the persisting ALK-antibody titers and observations of measurable anti-ALK T cell responses after—but not before—chemotherapy in a few patients." (PMID 29642597, 2018). "Patients with EML4-ALK fusion and other ALK rearrangements represent 3–7% of all NSCLC cases, usually associated with younger age, never smoking or light smoking history and adenocarcinoma histology (especially in those tumours harbouring signet-ring cell features)." (PMID 29662531, 2018). "However, tumor and host factors contributing to the individual immune response against ALK are still largely unknown." (PMID 29642597, 2018). "The recommendations for systemic anticancer therapy for stage IV NSCLC vary according to tumor histology, the patient’s performance status, and driver oncogene biomarker status, most frequently epidermal growth factor receptor (EGFR) mutation and anaplastic lymphoma kinase (ALK) translocation." (PMID 28644837, 2017). "We could show that miR-150 is a tumor suppressor miRNA in ALK(+) ALCL cells." (PMID 28771164, 2017). "Therefore, the Ventana IHC assay may be more sensitive than FISH for detecting ALK status in metastases and/or small biopsies which often contain only few tumour cells." (PMID 28887531, 2017). "Therefore, we suggested that a change in ALK status between the primary tumour and metastasis was not the cause of crizotinib resistance." (PMID 28887531, 2017). "The presence of EGFR gene mutations and, in particular, ALK gene rearrangement could be associated with the lack of PD-L1 expression on tumor cells." (PMID 28969070, 2017). "Provisional data that we have obtained points to a trend of increasing survival and slower tumor growth kinetics in offspring born from anti-ALK vaccinated mothers, as compared to those from control mothers, accompanied by a specific antibody response against ALK borne by mothers and offspring." (PMID 28763018, 2017). "However, given the involvement of ALK across the spectrum of all spitzoid tumors, the gene may have limited utility in helping to clarify the tumor’s malignant potential." (PMID 28895885, 2017). "As we already suggested earlier, a subset of patients (showing gene mutations in PIK3CA, HRAS, KRAS, NRAS and BRAF or ALK translocation) could benefit from a systemic treatment with a PI3K, MEK, BRAF or ALK inhibitor in the case of unresectable or metastasized tumor stage." (PMID 29312620, 2017). "Recently, broad studies of tumor biology have allowed developing particular targeted therapies for patients with specific mutations in multiple driver genes, including the epidermal growth factor receptor (EGFR), anaplastic lymphoma kinase (ALK), as well as ROS proto-oncogene 1 (ROS1)." (PMID 28881856, 2017). "Furthermore, FISH results are often subjective, and tumor cells harboring ALK rearrangements may distribute asymmetrically due to intra-tumor heterogeneity." (PMID 27564104, 2016). "In addition, we observed an G1269A ALK mutation in the post-treatment tumor, which was not detectable in the pre-treatment tumor sample using ddPCR." (PMID 27045755, 2016). "Therefore, NLRR1 and ALK tended to be oppositely expressed among different tumours." (PMID 27604320, 2016). "Of the 12 ALK-positive tumors, three showed strong homogeneous staining in more than 75 % of the tumor cells, while lower immunoreactivity scores and a varying pattern with regard to staining intensity and fraction of positive tumor cells was observed for the remaining nine tumors." (PMID 27495736, 2016).
tumor (continued). "To evaluate whether ongoing recombinase activity could occur in established ALK+ ALCL tumours, we looked for RAG1 transcripts in 52 cases, but all were negative, as were all the three ALCL cell lines tested in contrast to the immature T-ALL cell lines arrested at a thymic stage of development." (PMID 26753883, 2016). "Besides, crizotinib and ceritinib that both show high tumor response rates, next generation ALK inhibitors such as alectinib, brigatinib (AP26113) and lorlatinib (PF-06463922) are under development and show high response rates in diverse resistance associated ALK mutants." (PMID 27045755, 2016). "Even though ALK translocations are generally mutually exclusive compared to EGFR and/or KRAS mutations, more recently the complexity of clonality, the resistance mechanisms, and the selective pressure of antiblastic treatments on tumour growth have made this principle more debatable." (PMID 27433281, 2016). "They stained two other cases from their archive and found the same result and thus they conclude that ALK-positive DLBCL should be considered in the differential diagnosis when evaluating a Napsin A-positive tumor of poorly differentiated morphology and of unknown primary." (PMID 27398102, 2016). "As autopsy specimens had an ALK R1181C mutation, PDX tumor bearing animals were treated with the pan-kinase inhibitor lestaurtinib but demonstrated no decrease in tumor growth, suggesting that single agent kinase inhibitor therapy may be insufficient in similar cases." (PMID 26696773, 2015). "Therefore, it is tempting to speculate that the low expression of miR-146a and miR-155 might influence the unique immunophenotype of the ALK+ ALCL tumor cells and the tumor microenvironment." (PMID 25688981, 2015). "In conclusion, the assay that we have developed offers a reliable, noninvasive blood test to assess ALK mutational status at F1174 and R1275 hotspots and should help clinicians to identify patients showing an ALK mutation in particular when no tumor tissue is available." (PMID 25653133, 2015). "In addition, the tumor cells were positive for ALK, exhibiting a cytoplasmic pattern." (PMID 26178751, 2015). "However, tumor samples are not always available for analysis of ALK mutational status in particular at relapse." (PMID 25653133, 2015). "In this context, RMS tumours that overexpress ALK may constitute a subset at high likelihood for drug response, whereas those harbouring mutations in the kinase domain or expressing wild-type ALK receptor at physiological levels may not be sensitive to targeted treatments." (PMID 26147305, 2015). "Although multivariate analysis could not be performed due to the small sample size of crizotinib-treated patients, we did demonstrate by univariate analysis that tumor with moderate and strong ALK expression marginally predicted improved OS2 and significantly predicted a decreased risk of death." (PMID 24404167, 2014). "Among the 5,291 coding somatic mutations found in an aggregate of 240 matched tumour/normal samples, we found 26 overlapping variants in SH-SY5Y inside 24 genes among which 9 were rare amino-acid changing mutations inside 7 genes (ALK, FOXD4L1, HLA-DRB1, NBPF10, NBPF14, PABPC3, TEKT4)." (PMID 25528190, 2014). "This was further supported by experiments in TPM3-ALK (conditional onco-ALK) MEF cells which showed that both ALK and HIF1α expression are a prerequisite for miR-16 downregulation; in agreement with these findings, increased miR-16 expression in vivo reduced angiogenesis and tumour growth." (PMID 25197665, 2014).
tumor (continued). "ALK-rearranged CTCs harboring this unique rearrangement expressed a mesenchymal phenotype, suggesting that these cells may have derived from the clonal selection of tumor cells harboring greater invasive and migratory properties." (PMID 25414829, 2014). "The finding that several tumor types have been identified that have ALK as an oncogenic driver regardless of their cell of origin has prompted the creation of the term “ALKomas” implying a “beyond organ” concept classification assuming consequently responses to ALK inhibitors such as crizotinib." (PMID 25083769, 2014). "Interestingly, in these studies only 36 and 28% of the critzotinib resistance was due to secondary rearranged ALK gene mutations not found in the tumor at the initial diagnosis [99,134, respectively]." (PMID 24955213, 2014). "Interestingly, JoMa1-ALK tumors and their derived cell lines upregulated Myc endogenous expression, resulting from ALK activation, and both ALK and Myc activities were necessary to confer tumorigenic properties on tumor-derived JoMa1 cells in vitro." (PMID 24947326, 2014). "Thus, ALK-F1174L strongly accelerated MONC-1 cell-derived tumor growth." (PMID 24947326, 2014). "In addition, this tumor shows a MYCN as well as an ALK amplification." (PMID 25161957, 2014). "Additionally, anaplastic lymphoma kinase (ALK) was weakly expressed in the tumor cells." (PMID 23936706, 2013). "To gain insights into etiology and carcinogenic mechanisms we conducted analyses to compare allelotypes of 35 ALK fusion-positive and 95 -negative tumours using single nucleotide polymorphism (SNP) arrays and especially designed software which enabled precise global genomic profiling." (PMID 23289484, 2013). "Although debate exists as to whether IMT is a pseudotumor or a neoplasm, the concept of IMT as a neoplasm was recently solidified with the discovery of cytogenetic aberrations and the subsequent recognition of ALK gene rearrangements on the short arm of the chromosome as a recurrent aberration." (PMID 22405533, 2012). "In cancer, these developmental programs are frequently co-opted to support tumor growth, angiogenesis, immune evasion, and microenvironmental remodeling via pathways such as PI3K/AKT, MAPK, and ALK." (PMID 41955968, 2026). "The morphology and immunohistochemical profile, including focal expression of smooth muscle actin and S-100, plus diffuse staining for ALK protein, were compatible with an IFS-like neoplasm." (PMID 41439260, 2026). "While molecular targeted therapies, including EGFR and ALK inhibitors, have transformed first-line treatment, their effectiveness in advanced NSCLC is frequently constrained by acquired resistance and tumor heterogeneity." (PMID 41579221, 2026). "The RET and ALK alterations were identified in a midpole nodule, whereas BRAF positivity was seen in a separate lower pole tumor." (PMID 42039113, 2026). "Alectinib demonstrated potent antitumor activity in both in vitro and in vivo models against tumor cell lines harboring ALK gene alterations, including NSCLC cells with the EML4-ALK fusion." (PMID 40870997, 2025). "Wild-type LUAD demonstrated a higher number of tumor-infiltrating CD8+ T-cells, while in tumors with EGFR and ALK alterations, the number of CD8+ T-cells was much lower, and KRASm LUAD was heterogeneous in terms of tumor-infiltrating CD8+ cells count." (PMID 40809430, 2025). "Despite this low expression, our results establish that even minimal ALK levels are sufficient to trigger RDAA and drive tumor progression." (PMID 40246819, 2025). "Fluorescent in situ hybridization (FISH), immunohistochemistry (IHC), and sequencing of DNA and RNA are standard methods to detect ALK and ROS1 fusions, but they are costly, time-consuming, and require adequate tumor tissue." (PMID 40739404, 2025). "Five of nine (56%) patients with CD25-low ALK+ ALCL and nine of thirty-eight (24%) patients with CD25-high neoplasms died." (PMID 40507248, 2025).
tumor (continued). "Y5-3, however, effectively downregulated ALK and CDK4, blocking cell cycle progression at the G0/G1 phase, reducing colony formation, and significantly diminishing tumour volume and weight in vivo." (PMID 40793752, 2025). "None of the included NSCLC patients bared targetable genetic tumor alterations (EGFR, ALK, or ROS1)." (PMID 40091413, 2025). "Among all ALK+ ALCL patients, those who were younger (<30 years) and had CD25-high neoplasm had the longest OS, with a long-term OS rate of 89%." (PMID 40507248, 2025). "We employed targeted next-generation sequencing to analyze seven actionable driver genes - EGFR, KRAS, NRAS, BRAF, ALK, ROS1, and PIK3CA - in formalin-fixed, paraffin-embedded tumor specimens from Vietnamese NSCLC patients." (PMID 40502411, 2025). "Exosomes released into circulation possess the potential to provide insights into tumor status, as evidenced by the correlation between plasma exosomal microRNAs and the efficacy of immunotherapy in EGFR/ALK wild-type advanced NSCLC." (PMID 41573685, 2025). "DNA nanomicelles loaded with doxorubicine and ALK-specific siRNA induced apoptosis of ALCL K299 cells in vitro and inhibited tumor growth in vivo, potentially representing another therapeutical approach to treat these tumors." (PMID 40565334, 2025). "Similar anti-tumor activity is observed in NGP and COG-N-424x xenografts, ALK WT models with varying levels of ALK overexpression and MYCN status, as observed in patient tumors." (PMID 40813394, 2025). "This fusion, involving the KIF5B and ALK genes, creates an oncogenic kinase that activates downstream pathways, such as STAT3, promoting tumor growth, migration, and invasion." (PMID 39810398, 2025). "Genetic alterations in oncogenic drivers such as EGFR, ALK, KRAS, BRAF, MET and others can modify immunogenicity and impact the tumor microenvironment (TME)." (PMID 40809430, 2025). "Compared with CD25-high ALK+ ALCL cases, CD25-low neoplasms were more often positive for surface CD3 (100% vs. 3%, p = 0.001) and CD8 (57% vs. 14%, p = 0.03)." (PMID 40507248, 2025). "Next, we investigated the role of PTPN2 in tumor growth and survival by introducing control or PTPN2‐targeting sgRNAs into ALK+ ALCL cell lines using CRISPR/Cas9 technique." (PMID 40734623, 2025). "Ceritinib treatment slowed tumor growth and improved survival in mice injected with RDAA and ALK-rearranged (EML4-ALK) H1299 cells compared with control mice." (PMID 40246819, 2025). "ALK and ROS1 are involved in chromosomal rearrangements that result in the production of constitutively active, tumor-driving receptor tyrosine kinases, and patients with ALK or ROS1 fusions are recommended specific targeted therapies." (PMID 40739404, 2025). "Histopathological examination revealed that the largest tumor was an IMT with abundant myxoid matrix, positive for anaplastic lymphoma kinase (ALK), and ALK gene rearrangement." (PMID 40557015, 2025). "Therefore, the approaches discussed in Section 2.2 and Section 3.5, focusing on targeting MYCN and ALK, may be used not only to target tumor growth, but to alleviate immune evasion mechanisms, and their effect could be further potentiated by combining them with immunotherapeutic approaches." (PMID 40507292, 2025). "AH-cfDNA revealed additional somatic copy-number alterations, including amplifications (i.e., MDM4 and ALK) and deletions (i.e., BRCA2), indicating progressive clonal tumor evolution." (PMID 41465072, 2025). "It appears that ALK-positive ALCL tumor, or at least a representative cell line, presents many receptors and/or ligands, which participate in the anti-tumor immune response and possibly skew it toward its growth." (PMID 41469691, 2025). "In tumor xenografts, ALK knockdown was shown to reduce VEGFA expression, decrease tumor vessels in tumor xenografts, and control tumor growth." (PMID 41295262, 2025).
tumor (continued). "Genetic mutations commonly found in NSCLC, such as alterations in KRAS, EGFR, anaplastic lymphoma kinase (ALK), and liver kinase B1 (LKB1), drive distinct metabolic reprogramming in tumor cells." (PMID 40469185, 2025). "ALK was upregulated in a subset of tumors, particularly in non-smokers, while PDCD1 was predominantly expressed in immune-rich tumor microenvironments." (PMID 40927719, 2025). "Using spatial histological inferences from experimental models of ALK+ NSCLC, we found that peristromal niches protected tumor cells from therapeutic elimination in vivo, enabling in vivo persistence." (PMID 40313737, 2025). "Y5-3 features a disulphide (-S-S-) bond extended from the ALK-targeting PROTAC linker, conjugated to palbociclib (a CDK4/6 inhibitor), and cleaved by GSH to selectively release its functional moieties in tumour cells." (PMID 40793752, 2025). "To mimic fibroblast–tumor cell interactions in the TME in vitro, we established spheroid co-culture models of ALK-driven NSCLC cell lines and CAFs." (PMID 40524253, 2025). "In ALK+ subtypes, CD147 promotes tumor growth and invasion by enhancing miR-146a-mediated aerobic glycolysis." (PMID 41479915, 2025). "While preoperative diagnosis of IMTs is generally challenging, neoadjuvant ALK inhibitor therapy is specifically considered in cases where IMT has been confirmed through preoperative tissue sampling and where the tumor is deemed initially unresectable." (PMID 40234278, 2025). "Also, OncoPrism-HNSCC leverages the same FFPE patient tumor RNA used for ICI response prediction to identify rare cases where oncogenic rearrangements in NTRK1/2/3 or ALK genes may occur, and which may indicate the use of potentially highly effective targeted therapies." (PMID 39773366, 2025). "After covariate matching 4:1 with the ALK fusion-positive cohort (by patient characteristics, tumor type, ECOG PS, number of prior therapies, practice type, and timing of CGP), the matched ALK-WT cohort included 88 patients." (PMID 40338218, 2025). "In ALK+ ALCL, CD147–MCT1 complexes are essential for glucose metabolism and tumor growth, while CD147 knockdown significantly reduces glucose uptake and induces mitochondrial dysfunction." (PMID 41479915, 2025). "EGFR, ALK, and Kirsten rat sarcoma (KRAS) drive tumor progression by increasing cell survival and proliferation in bone metastasis." (PMID 41245887, 2025). "It has been widely used to detect druggable tumor-specific genes such as EGFR, ALK, ROS1, BRAF, KRAS, NTRK1/2/3, ERBB2, RET, and MET in patients with NSCLC." (PMID 41515905, 2025). "Together, these data suggest that loss of HDAC1 protein and activity results in a shift of the immunophenotype of ALK+ tumor cells, with higher numbers of cells expressing the TCR, seemingly facilitating increased tumor cell dissemination." (PMID 40175628, 2025). "Genome-wide CRISPR activation screen in NB cells revealed that PIM1 drives resistance to ALK inhibitors brigatinib or ceritinib, and the combination of AZD1208 with ceritinib significantly delayed tumour growth in ALK mutant NB PDX models." (PMID 41511287, 2025). "FISH for ALK gene rearrangements is widely used; however, false-negative results may occur, particularly in cases with abundant inflammation that obscures tumor cells or intrachromosomal inversions (e.g., EML4::ALK fusion), which FISH can sometimes miss due to inadequate probe spacing." (PMID 40282503, 2025). "Collectively, these results demonstrated that AC484 induced apoptosis and inhibited tumor growth in ALK+ ALCL, highlighting its therapeutic potential for ALK+ ALCL patients." (PMID 40734623, 2025). "The oncogenic ALK fusion continuously engages multiple downstream signaling pathways, including PI3K-AKT, RAS-MAPK, and JAK-STAT, thereby promoting tumor cell proliferation, migration, and evasion of apoptosis." (PMID 41614760, 2025).